IL6 (interleukin 6)
Diseases named in the same sentence as IL6 in open-access papers (continued):
Sharing a sentence is not in itself a finding about the gene and the disease.
COVID-19 (continued). "For instance, adult patients with community-acquired pneumonia have a mean serum IL-6 of 477 pg/ml, and COVID-19 patients with delirium have a mean serum IL-6 of 229.9 pg/ml." (PMID 36781081, 2023). "Angiotensin II stimulates/induces the expression of a multifunctional IL-6 thus contributes to cytokine storm with poor outcome/prognosis in COVID-19 patients." (PMID 38057707, 2023). "When administered intravenously, treatment outcomes in COVID-19 patients with pneumonia were mixed, as elevated IL-6 levels are only detectable in critical and severe infections." (PMID 37112923, 2023). "Interleukin 6 (IL-6) is a pivotal proinflammatory cytokine in COVID-19 pathogenesis, and IL-6 inhibition can improve clinical outcomes and survival of patients with severe disease." (PMID 37376587, 2023). "Here, we show that IL-6 serum levels correlated with the level of care in hospitalised COVID-19 patients." (PMID 37917760, 2023). "Another group of researchers confirmed that patients with severe COVID-19 have elevated serum levels of IL-2, IL-6, IL-10 and TNF-α." (PMID 36766583, 2023). "Post-mortem investigations of COVID-19 patients revealed considerable lymphocyte mortality in lymph follicles and paracortical regions of lymph nodes, which may have been caused, among other things, by macrophage-derived IL-6 that directly promoted lymphocyte necrosis." (PMID 36679947, 2023). "A significant number of genes related to inflammation, such as IFN-γ and -α responses; TNFA, IL-6, and IL-2 pathways; inflammatory response; and allograft rejection, were highly enriched in COVID-19 kidneys compared with healthy controls." (PMID 36749641, 2023). "RECOVERY trial results indicate that tocilizumab (anti-IL-6 drug), along with corticosteroids, improved the survival in patients with COVID-19 who had hypoxia and systemic symptoms." (PMID 38094124, 2023). "The severity of COVID-19 elevated IL-6 or ferritin levels and younger age are considered strong risk factors for liver injury during hospitalization and are associated with mortality." (PMID 37654571, 2023). "Considering the crucial role of IL-6 in COVID-19 prognosis, many studies have targeted IL-6 pathways as a potential therapeutic approach." (PMID 37371831, 2023). "Excessive production of certain cytokines, such as IL-6, has been identified as a major factor contributing to the inflammatory response observed in COVID-19." (PMID 38125571, 2023). "Similar results supporting this finding were conducted in a group of 12 COVID-19 patients and found that decreased HRV was associated with increased levels of inflammation, as measured by C-reactive protein (CRP) and interleukin-6 (IL-6) levels." (PMID 37629687, 2023). "The increase in serum IL6 level is related to severe COVID-19 and is a good biomarker for distinguishing between severe and mild cases." (PMID 37564653, 2023). "In patients admitted to medical emergencies with a confirmed diagnosis of COVID-19, it is important to perform a joint evaluation of demographic characteristics, clinical parameters, interleukins (IL-2, IL-6, IL-7, IL-10, IL-17) and sP-selectin." (PMID 36835858, 2023). "Among 191 COVID-19 patients, Roche IL-6 levels had a median (interquartile range) of 62.0 pg/ml (24.7–224.6) and MSD IL-6 levels had 22.0 pg/ml (9.3–74.7)." (PMID 37650680, 2023). "Consistently, we found the plasma levels of IL-5, IL-6, IL-8, IL-10 and IP-10 to be significantly higher in severe COVID-19 patients compared with control plasma." (PMID 37207201, 2023). "Observational studies showed elevated levels of different cytokines in COVID-19 patients, such as TNFα, IL-1β, IL-6, IL-8, IL-10, and IL-17." (PMID 36983830, 2023). "One meta-analysis of IL-6 concentration levels found that patients with complicated COVID-19 had 2.9-fold higher levels than those with uncomplicated disease." (PMID 37124230, 2023).
COVID-19 (continued). "Tocilizumab, a monoclonal anti-IL6 receptor antibody, and baracitinib, a monoclonal antibody that inhibits JAK1 and JAK2 (which are activated in response to IL6 signaling), have also demonstrated initial clinical efficacy in COVID-19 patients." (PMID 37090709, 2023). "The comparison of a 6-gene signature (ACE2, TMPRSS2, AR, TLR7, IL6, and IRF5) was made to explore the sex-based differences associated with COVID-19." (PMID 36992366, 2023). "Our data show that plasma D-dimer concentration in COVID-19 patients was directly related to IL-6 and TNF, and indirectly related to IL-10." (PMID 37408073, 2023). "Serum IL-6 level was higher in ENA-positive COVID-19 patients than in ENA-negative COVID-19 patients." (PMID 38107861, 2023). "The overexpression of IL-6 and its receptor in COVID-19 leads to the hyperactivation of endothelial cells." (PMID 37628963, 2023). "A logistic regression was performed to predict the determinants of COVID-19 mortality by including covariates with p-value < 0.2 (ischemic heart diseases, asthma, IL-6, D-dimer and clinical improvement)." (PMID 37111389, 2023). "The elevated inflammatory markers including CRP, D-dimer, ferritin, and IL-6 in severe COVID-19 infected individuals support the inflammatory "cytokine storm" response theory." (PMID 38313184, 2023). "Further large-scale clinical research is required to emphasize the link between IL-6 and COVID-19 outcomes." (PMID 37960722, 2023). "A summary analysis of 182 children hospitalized with COVID-19 had a high proportion of serum interleukin IL-2 and IL-6." (PMID 36982944, 2023). "The IL-6 concentration is known to predict the development of the severe COVID-19 and of the hypoxemia that will need hospitalization." (PMID 36838284, 2023). "Collectively, this study considers and attributes 5.186 pg/ml as the mean value of IL-6 in healthy individuals to 9 studies, which is obviously lower than that estimated for acute or long COVID-19." (PMID 37095536, 2023). "The exaggerated expression of IL-6 and IL-6 receptor in COVID-19 leads to endothelial cell hyperactivation and a large amount of tissue factor is released, both processes leading to infection-induced coagulopathy." (PMID 36901751, 2023). "IL-6 is produced in response to systemic inflammation, and, thus, is important in severe COVID-19 and respiratory failure." (PMID 37278822, 2023). "Being both P2X7R and NLRP3 tightly associated to the release of inflammatory cytokines, a reasonable anticipation is that their blood levels in COVID-19 should parallel that of the cytokines typically overexpressed in this disease, e.g., IL-6 and IL-10." (PMID 37215142, 2023). "High cytokine levels such as IL-6 and IL-10 as well as reduced CD4+ T lymphocytes were reported to be potential risk factors in patients with COVID-19 developing severe liver injury." (PMID 36902854, 2023). "Our novel prediction model based on time-series analysis of patient sera revealed a number of candidate proteins predicting changes in IL-6 and D-dimers as surrogates for hyperinflammatory and/or thrombotic responses in severe COVID-19 disease courses." (PMID 37834869, 2023). "Evidence from clinical studies indicates that the severity of COVID-19 is positively associated with chemokine and inflammatory cytokine levels in the plasma of patients, such as TNF-α, IL-1β, IL-6, CCL2, CCL8, and CXCL9." (PMID 38104081, 2023). "Recently, a higher percentage of GM-CSF+ IL-6+ CCR6+ Th17 cells has been detected in the blood circulation of COVID-19 patients." (PMID 36793739, 2023). "In response to high levels of IL-6 in COVID-19 patients, many hospitals use IL-6 antagonists to reduce inflammatory responses." (PMID 37310657, 2023). "In critically unwell patients with COVID-19, increases in IL-6: A1AT predicted a prolonged ICU stay and mortality, whereas improvement in IL-6:A1AT was associated with clinical resolution." (PMID 36831051, 2023).
COVID-19 (continued). "Evidence suggests that dysregulated inflammation with exacerbated production of inflammatory cytokines, such as IL-1β, IL-6, and IL-8, plays a significant role in patients with severe COVID-19." (PMID 37018291, 2023). "The mean values of IL-6 and sIL-6R were higher in COVID-19 patients than in the healthy control group." (PMID 37887780, 2023). "I the multivariate analysis, IL-6 values at 24 h ≥ 11, NLR values at 24 h ≥ 22, and NLR values at 72 h ≥ 14,were associated with 28-day mortality in patients with severe COVID-19 living at high altitude (p < 0.05)." (PMID 36675573, 2023). "As mentioned, IL-6 plays an important role in the exhaustion and dysfunction of NK cells in patients with COVID-19, so the use of an IL-6 inhibitor called tocilizumab can prevent NK cell exhaustion." (PMID 36936055, 2023). "The findings of the current study confirmed the literature data showing a statistically significant relationship between the increased levels of IL-6 in moderate vs mild COVID-19 patients and taste disorders." (PMID 35801415, 2023). "In another article, the authors reported a difference in the concentration of IL-6 in COVID-19 patients admitted to the ICU with hypoxemic respiratory failure compared to reference values." (PMID 36835858, 2023). "Serum IL-6 levels are markedly elevated in patients with severe COVID-19 and predictive of mortality." (PMID 38090572, 2023). "Studies have shown that TNFα and IL-6 are highly elevated in the blood of patients with severe COVID-19." (PMID 36482706, 2023). "Most COVID-19 patients included in this study had lymphopenia, eosinopenia, neutrophilia, increased inflammatory and coagulation indexes, and augmented sNLRP3, IL-6 and IL-10 levels." (PMID 37215142, 2023). "They found that high IL-6 levels, CRP and hypertension were independent risk factors of COVID-19 severity." (PMID 38099004, 2023). "A study conducted on COVID-19 patients receiving infliximab has revealed a drop in serum IL-6 as well as a decrease in deaths." (PMID 37163438, 2023). "Recent reports demonstrate that IL-6 and TNF-α were overexpressed in COVID-19 patients, causing inflammation." (PMID 36817449, 2023). "Genetic analyses (Mendelian randomisation (MR)) have previously predicted the success of IL-6 inhibition in COVID-19 and other conditions." (PMID 36716318, 2023). "In coronavirus disease 19 (COVID-19) patients, higher serum IL-6 concentrations imply hyperinflammatory responses that correlate with considerable disease severity and death." (PMID 37214473, 2023). "In a number of ongoing COVID-19 clinical trials, IL-6/IL-6R inhibitors were employed preliminarily, and further inter-clinical trials are presently underway." (PMID 37124230, 2023). "TNF and IL6 showed significant upregulation in COVID-19 patients, while the expression changes of the other targets were relatively minor." (PMID 38050310, 2023). "We found that the IL-6 levels were significantly higher in the COVID-19 patients and in the non-COVID-19 CKD patients compared to the healthy volunteers." (PMID 36983566, 2023). "The regulatory mechanisms of reduced mHLA-DR expression in severe/critical COVID-19 patients are less well understood, but IL-6 and IL-10 are similarly thought to be possible drivers to reduce mHLA-DR expression in the disease." (PMID 36834656, 2023). "The highest levels of IL-6 were found in COVID-19 patient with AKI with a median (SD) of 91.16 (77.89–166.88) pq/ml, ARDS (SD) 83.65 (25.15–252.58), oxygen saturation <95% (SD) 81.09 (45.08–252.58), and thrombocytopenia (SD) of 80.73 (51.3–52.58)." (PMID 37889917, 2023). "As an illustration, the application of tocilizumab, an IL-6 inhibitor, has been demonstrated to better the outcomes of COVID-19 patients." (PMID 37958192, 2023). "In severe to critical COVID-19, tocilizumab, an interleukin-6 antagonist, is used on compassionate grounds for treatment of COVID-19 cytokine storm." (PMID 36937039, 2023).
COVID-19 (continued). "Among critically ill patients with COVID-19, serum IL-6 and IL-10 levels are usually higher, while serum GM-CSF, TNF- α, IFN-γ, IL-2 and IL-8 serve as ancillary cytokines with clinical prognostic value in contrast to patients without critical disease." (PMID 37568402, 2023). "Treatment with steroids resulted in lower BAL concentrations of IL6 compared to tocilizumab or antivirals, suggesting that innate immune responses primarily drive alveolitis in COVID-19." (PMID 38131885, 2023). "In COVID-19 ARDS, plasma IL-6 levels, a cytokine strongly associated with vasculopathy and endothelial cell dysfunction, positively correlated with endostatin." (PMID 37283766, 2023). "IL-6 is one of the most important proinflammatory cytokines, and its increased levels have been recorded in COVID-19 patients, especially in those with severe to critical disease." (PMID 38264533, 2023). "In contrast, when compared with patients in the acute phase using seven cohorts from seven studies, long COVID-19 patients had lower mean IL-6 levels (mean difference = − 14.49 pg/ml, 95% CI = − 24.59 to − 4.39 pg/ml, I2 = 94%, P = 0.005)." (PMID 37095536, 2023). "A report describing the immunological profile of critically ill patients with COVID-19 suggested hyperactivation of the humoral immune pathway, including IL-6, as a critical mediator of respiratory failure, shock, and multiorgan dysfunction." (PMID 37095536, 2023). "Our team showed in a prospective observational cohort study of COVID-19 patients recruited in the Emergency Department (ED) of Lausanne University Hospital that sTREM-1- and IL-6-based algorithms were highly predictive of adverse outcome." (PMID 37752433, 2023). "These significant candidate biomarkers precede surges of IL-6 and D-dimers, which are prognostic markers and druggable targets of severe COVID-19 disease courses." (PMID 37834869, 2023). "The cytokines TNF-α, IFN-γ, IL-6, IL-2, and IL-10 quantified in newborns of mothers with COVID-19 showed high levels of expression compared with the control group." (PMID 36979888, 2023). "For example, several single-center investigations have used IL6 inhibitors to treat patients with COVID-19 and demonstrated certain clinical benefits." (PMID 36798115, 2023). "The IL-6 concentration and the severe form of COVID-19 are correlated with the presence of comorbidities." (PMID 36838284, 2023). "In elderly subjects, the decrease in circulating zinc concentration is associated with increased levels of cytokines such as IL-6, IL-8, and TNF-α, making it a qualified candidate as a prophylaxis and adjuvant treatment for COVID-19 in high-risk groups." (PMID 37405258, 2023). "This review article describes studies that correlate the long-term effects of COVID-19, especially in inflammatory conditions followed by coagulation with widely used biomarkers such as IL-6 for inflammation and D-dimer for coagulation." (PMID 37504277, 2023). "Analysis of data from 17 cohorts of the 16 articles that were involved in this study allowed us to calculate the mean values of IL-6 in the study subjects, including the long COVID-19 group, acute COVID-19 group, and healthy individual group." (PMID 37095536, 2023). "The inhibitory effect of VPA on inflammatory cytokines, such as TNF-α and IL-6, has been considered to prevent the generation of cytokine storms by COVID-19." (PMID 37762894, 2023). "Inflammatory markers, e.g., CRP, IL6, have been proven to significantly increase with disease progression in COVID-19 patients and can be used to differentiate the severity of patients’ condition." (PMID 37762549, 2023). "The inflammatory burden, as assessed by circulating IL-6 levels, was similar in the two groups (convalescent COVID-19: 1.74 (0.64, 4.97) pg/mL vs. control: 1.31 (0.98, 2.70) pg/mL, p = 0.95)." (PMID 36983234, 2023).
COVID-19 (continued). "For example, C-reactive protein (CRP), interleukin 6 (IL-6), and tumor necrosis factor alpha (TNFα) were significantly higher in patients with persistent symptoms after COVID-19 compared to patients that fully recovered." (PMID 37789266, 2023). "Serum levels of IL-1β, IL-6, IL-8, and TNF-α are elevated in COVID-19 patients and are associated with severe infection." (PMID 37376569, 2023). "IL-8 has been suggested as a target for anti-cancer drugs and has been associated with adverse outcomes in COVID-19 patients, along with TNF-α, IL-6, IL-1β, and IL-33." (PMID 37627815, 2023). "Tocilizumab, an IL-6 inhibiting monoclonal antibody indicated for treatment of severe COVID-19 has shown safety and efficacy in two previously refractory MG patients, and safety in a third patient in a small case series." (PMID 37712090, 2023). "Mitochondrial ROS mediate various signaling pathways, increase the expression of inflammatory cytokines (IL-6, IL-1β, TNF-α, etc.), and increase the risk of thrombosis in patients with COVID-19." (PMID 37834324, 2023). "During the stage of systemic inflammation in COVID-19, there is a significant increase in inflammatory biomarkers like IL-2, IL-6, and CRP, which are dramatically enhanced." (PMID 38106427, 2023). "The increase in the level of several biomarkers, including CRP, IL-6, as well as WBC counts, and D-dimer, has been associated with severe COVID-19." (PMID 37228441, 2023). "Pre-cannulation complete blood count and arterial blood gas labs, APACHE II and SOFA scores, and other stratifying markers of COVID-19-related systemic inflammation (i.e., IL-6 and c-reactive protein) were comparable between the survivors and non-survivors." (PMID 37305142, 2023). "The association of the IL6 genotype CC is also corroborated by the higher frequencies of COVID-19 symptoms among CC carriers, as well as by the slight increase of IL-6 levels in CC in comparison to GG genotypes during the active disease." (PMID 37243282, 2023). "This case demonstrates the low threshold to suspect HSV-1 reactivation and systemic illness in immunocompetent critically ill patients with COVID-19 who are treated with dexamethasone and IL-6 inhibitors." (PMID 37593250, 2023). "In conjunction with these results, patients treated with demeclocycline exhibited an increase in CD4+ T cell counts, which correlated with a decrease in IL-6 levels following treatment, suggesting the attenuation of COVID-19." (PMID 37612352, 2023). "The trend in IL6 and hsTnI levels in COVID-19 patients with myocardial injury was further analyzed, and the results showed that the changes in IL6 and hsTnI levels were strikingly similar." (PMID 37564653, 2023). "Administration of nano-curcumin has been reported to provide anti-viral action and to downregulate expression and secretion of the inflammatory cytokines IL-1β and IL-6 in COVID-19 patients." (PMID 37359549, 2023). "Cleaved caspase-1 and IL-18 were detected in the sera of COVID-19 patients and were positively correlated with disease severity, poor prognosis and other COVID-19 severity serum markers, including IL-6 and LDH." (PMID 36661317, 2023). "The levels of the inflammatory cytokines interleukin-6 (IL-6) and IL-10 appeared generally increased at diagnosis and decreased in post-COVID-19 patients." (PMID 37896963, 2023). "Increased WBC and neutrophil counts, lymphocytopenia, increased neutrophil-to-lymphocyte ratio, thrombocytopenia, elevated CRP, ferritin, D-dimer, and IL-6 levels have been associated with MIS and unfavourable clinical outcomes in COVID-19." (PMID 36830885, 2023). "Then, this activation leads to the increase of several inflammatory interleukins (such as IL-1β and IL-6) that are responsible for adverse clinical outcomes in COVID-19." (PMID 37674935, 2023).